GINS1 (GINS complex subunit 1)
Description:
Required for correct functioning of the GINS complex, a complex that plays an essential role in the initiation of DNA replication, and progression of DNA replication forks. GINS complex is a core component of CDC45-MCM-GINS (CMG) helicase, the molecular machine that unwinds template DNA during replication, and around which the replisome is built.
Synonyms: KIAA0186; PSF1; IMD55
Tractability: Small molecule: a structure with a bound ligand is known. PROTAC: ubiquitination databases record sites on it.
Gene: Protein-coding gene on chromosome 20 (25,391,008 to 25,452,700, forward strand). Ensembl gene ENSG00000101003.
Subcellular location: Nucleus; Chromosome
Subcellular location (Human Protein Atlas): Nucleoplasm
Pathways (Reactome):
DNA Replication: Unwinding of DNA
Gene Ontology:
Molecular function: protein binding
Biological process: DNA replication; DNA strand elongation involved in mitotic DNA replication
Cellular component: CMG complex; cytoplasm; GINS complex; nucleus; nucleoplasm; chromosome
Genetic constraint (gnomAD): Loss-of-function variants: 2 observed, 1.88 expected, observed/expected ratio (o/e) 1.07, 90% interval 0.38 to 1.89. That is too few expected variants to judge how well the gene tolerates losing a copy. Missense variants: 31 observed, 34.26 expected, observed/expected ratio (o/e) 0.9, 90% interval 0.68 to 1.22. Synonymous variants: 19 observed, 15.03 expected, observed/expected ratio (o/e) 1.26, 90% interval 0.88 to 1.79.
Gene-disease validity (ClinGen):
ClinGen rates the evidence that GINS1 causes each of these diseases.
combined immunodeficiency due to GINS1 deficiency (autosomal recessive): Moderate.
Homologues: Orthologues: chimpanzee GINS1 (100% identical), dog GINS1 (95% identical), pig GINS1 (94% identical), guinea pig GINS1 (94% identical), mouse Gins1 (93% identical), tropical clawed frog gins1 (91% identical), macaque GINS1 (88% identical), rat Gins1 (85% identical), zebrafish gins1 (85% identical), Drosophila melanogaster Psf1 (52% identical), Caenorhabditis elegans psf-1 (39% identical).
Diseases named in the same sentence as GINS1 in open-access papers:
GINS1 is named in the same sentence as 55 diseases in open-access papers, as found by Europe PMC text mining. Sharing a sentence is not in itself a finding about the gene and the disease. The quoted sentences say what the papers report.
breast cancer (8 papers, 2017 to 2025). A primary or metastatic malignant neoplasm involving the breast. "Among the genes activated by ZNF518B, CERK is associated with highly aggressive human breast cancer and GINS1 expression correlates with proliferation of breast cancer cells and with poor prognosis in hepatocellular carcinoma." (PMID 33801071, 2021). "The initial editing predictions for MDM2, GINS1, and F11R, obtained from the TCGA breast cancer patient dataset was experimentally validated." (PMID 40381037, 2025). "When the miR-101-5p-associated pathways in breast cancer were assessed using RNA-seq, a particular group of genes, HMGB3, ESRP1, GINS1, TPD52, SRPK1, VANGL1, and MAGOHB, were suggested to be associated with a poor prognosis of BC." (PMID 38132441, 2023). "GINS complex were found to be overexpressed in breast cancer, lung cancer, etc, and high GINS1 transcriptional activity were correlated with high proliferative and metastatic activity, serial transplantation potential." (PMID 34414190, 2021). "Many studies have shown that GINS1 is up-regulated in several cancer types including lung, colon, prostate, colorectal and breast cancers." (PMID 29443924, 2018). "Using TCGA RNA-seq data, we identified differentially edited 3’UTRs in breast cancers and experimentally validated editing sites in the 3’UTRs of MDM2, GINS1, and F11R regulated by ADAR1 with protein level implications." (PMID 40381037, 2025). "We confirmed A-to-I(G) editing in the 3’UTRs of MDM2 (Mouse Double Minute 2 homolog), GINS1 (GINS Complex Subunit 1), and F11R (Junctional Adhesion Molecule A) in breast cancer cells." (PMID 40381037, 2025).
hepatocellular carcinoma (4 papers, 2021 to 2023). A malignant tumor that arises from hepatocytes. "GINS1 is essential for the establishment of DNA replication forks and the initiation of DNA replication and contributes to promoting hepatocellular cancer cell stemness and enhancing Sorafenib resistance." (PMID 38343446, 2023).
Immunodeficiency (4 papers, 2018 to 2022). Failure of the immune system to protect the body adequately from infection, due to the absence or insufficiency of some component process or substance. "For GINS1 (GINS complex subunit 1), the GINS complex is known to be essential for the initiation of eukaryotic DNA replication and diseases associated with it included immunodeficiency and neutropenia." (PMID 34034637, 2021). "Other components of the CMG helicase, including MCM4 and GINS1, have been linked to forms of primordial dwarfism similar to MGS, but they have been classified as clinically distinct due to the fact that they include immune deficiencies and/or adrenal insufficiency." (PMID 35603789, 2022).
melanoma (4 papers, 2007 to 2025). A malignant, usually aggressive tumor composed of atypical, neoplastic melanocytes. "The RAS/RAF/MAPK signaling pathway has been reported to be involved in GINS1-mediated tumor progression, and could be regulated by microRNA-340 to suppress the tumorigenic phenotype in melanoma." (PMID 40123906, 2025). "Among the genes that were downregulated by silencing this deacetylase are those that have been positively correlated with melanoma aggressiveness (e.g., NCAPG, CDKN2C, GINS1, and DHFR are all downregulated in the SSW30 clone)." (PMID 31091806, 2019).
synovial sarcoma (4 papers, 2020 to 2025). "Prior studies discovered that GINS1 could be a target of anlotinib which suppressed the proliferation of synovial sarcoma cells." (PMID 40123906, 2025). "Interestingly, GINS1 was identified as an anlotinib‐mediated downstream gene, and knockdown of GINS1 markedly inhibited the proliferation of synovial sarcoma cells." (PMID 31755218, 2020).
diffuse large B-cell lymphoma (3 papers, 2023 to 2025). "pointed out that FOXP1 transcriptionally activates GINS1 expression to promote diffuse large B‐cell lymphoma development." (PMID 38652109, 2024). "However, GINS1 remains poorly investigated in DLBCL (diffuse large B-cell lymphoma)." (PMID 37576391, 2023).
glioblastoma (3 papers, 2023 to 2025). The most malignant astrocytic tumor (WHO grade IV). "NFIX regulates the proliferation and DNA damage response of glioblastoma multiforme (GBM) cells through transcriptional activation of GINS1." (PMID 40000619, 2025). "The analysis reveals that GINS1 promotes glioblastoma cell proliferation and migration through the mediation of USP15 and TOP2A deubiquitination." (PMID 38301047, 2024).
liver cancer (3 papers, 2018 to 2023). An epithelial or non-epithelial malignant neoplasm that arises from the liver. "GINS1 was found to be related to poor prognosis in breast and liver cancer." (PMID 36910651, 2023). "Finally, survival analysis, based on clinical information from the TCGA-liver cancer datasets, revealed that the high expression of EZH2, GINS1, and TPX2 correlated positively with higher risk, CENPF and BUB1B were quite the contrary." (PMID 30100882, 2018).
lung carcinoma (3 papers, 2021 to 2022). "To further investigate the expression of GINS1 in tumors and its influence on survival time, we conducted a meta-analysis in lung cancer with the highest incidence." (PMID 36451247, 2022). "It has been demonstrated that GINS1 was highly expressed in various cancers, including intrahepatic cholangiocarcinoma, breast carcinoma, lung cancer, and colorectal cancer." (PMID 36451247, 2022). "High expression of GINS1 was found in breast and lung cancer, and was related to enhanced ability in tumor proliferation and poor patient prognosis." (PMID 34414190, 2021). "Results showed that the mRNA expression of BIRC5, SHCBP1, CCNA2, SKA3 and GINS1 in LUAD and LUSC tissues were all significantly higher than that in normal tissues, whereas only BIRC5 and CCNA2 protein expression in lung cancer tissues were much higher than those in the normal lung tissues." (PMID 34806315, 2022). "Since COVID-19 virus infects the lung first, coupled with the high expression of GINS1 in LUAD and LUSC, we hypothesize that the cell lines of lung cancer have the highest sensitivity among these 11 cancers." (PMID 36451247, 2022).
osteosarcoma (3 papers, 2021 to 2022). A usually aggressive malignant bone-forming mesenchymal neoplasm, predominantly affecting adolescents and young adults. "The immunofluorescence imaging results exhibited GINS1/2/3/4 proteins (green) mainly localized to nucleoplasm (blue) in the osteosarcoma cell line (U2OS)." (PMID 36092720, 2022). "By interrogating CCLE, we detected the transcription level of GINS members in many types of cancer cell lines, and got the conclusion that GINS1, GINS2 GINS3 and GINS4 were highly expressed in sarcoma cell lines including Ewing's sarcoma, osteosarcoma and chondrosarcoma." (PMID 35896011, 2022).
prostate carcinoma (3 papers, 2017 to 2023). A carcinoma that arises from epithelial cells of the prostate gland. "What’s more, the researcher found that the expression of GINS1 was significantly associated with prostate cancer grade and overall survival, which was regarded as a prognostic biomarker for prostate cancer." (PMID 36451247, 2022). "TRIP13 promotes early steps of the DNA double-strand break repair and its presence was associated with progression in prostate cancer; and GINS1 plays a role in the initiation of DNA replication and has been part of a gene-set associated with outcome in early stage non-small cell lung cancer." (PMID 28968952, 2017).
sarcoma (3 papers, 2022 to 2024). A usually aggressive malignant neoplasm of the soft tissue or bone. "Analyses of co-expressed genes of GINS1 and the association between GINS1 in sarcoma were conducted in the Barretina dataset." (PMID 35896011, 2022). "Our study indicated that the value of GINS1 in prognosis of human sarcoma was confirmed by 131 sarcoma patients." (PMID 35896011, 2022). "Using the GEPIA dataset, we compared the expression of GINS mRNAs in sarcoma and normal tissues, it indicated that the expression levels of GINS1, GINS2 and GINS3 in sarcoma were statistically higher than in normal samples." (PMID 35896011, 2022). "Kaplan–Meier Plotter Database analysis showed that higher expression levels of GINS1/2/3/4 mRNA correlated with lower OS in sarcoma." (PMID 36092720, 2022). "In terms of Disease-free survival (DFS), high expression of GINS1/2/3 also predicted shorter DFS in sarcoma." (PMID 36092720, 2022). "ROC analysis of the GSE40021 dataset showed that upregulated GINS1/2/3 expression was closely related to sarcoma metastasis." (PMID 36092720, 2022). "Our comprehensive analysis identifed 675 genes and the top 50 most frequently genes co-expressed with GINS1/2/3/4 in sarcoma by UALCAN and cBioPortal database, respectively." (PMID 36092720, 2022). "Our results showed that GINS1 transcription was significantly elevated in sarcoma tissue, and GINS1 was overexpressed in sarcoma cell lines." (PMID 36092720, 2022). "Meanwhile, it was found that at the RNAseq level, GINS1/2/3/4 expression in sarcoma ranked eighth, fourth, sixth and third among various cancer cell lines." (PMID 36092720, 2022). "In terms of Recurrence-free survival (RFS), high expression of GINS1/2/3/4 predicted a poorer RFS in sarcoma." (PMID 36092720, 2022). "The CCLE database analysis showed that GINS1/2/3/4 were relatively highly expressed in sarcoma compared to most cancer cell lines." (PMID 36092720, 2022). "Finally, THUMPD3-AS1 was found to be a lncRNA that regulates most mRNAs of GINS genes (GINS1/2/4) in sarcoma by binding to hsa-miR-26a-5p and hsa-miR-29a-3p simultaneously." (PMID 36092720, 2022). "We found that increased mRNA expression of GINS1/3 in sarcoma was closely related to poorer OS." (PMID 36092720, 2022). "GINS1, GINS2 and GINS4 were positively correlated with the immune cell infiltration in sarcoma microenvironment." (PMID 35896011, 2022). "The GEPIA and Kaplan-Meier Plotter was used to make the investigation of the prognostic ability of GINS1, GINS2, GINS3 and GINS4 expression levels in sarcoma." (PMID 35896011, 2022). "In addition, the mRNA expression levels of the four GINS family members (GINS1, GINS2, GINS3, GINS4) were all higher in sarcoma tissue." (PMID 38473259, 2024). "The prognostic relevance tested was also obvious, increased expression of GINS1, GINS2, GINS3 and GINS4 may provide us new therapeutic targets for the treatment of sarcoma." (PMID 35896011, 2022). "The high expression level of GINS1, GINS2 and GINS4 could reduce immune cell infiltration in the sarcoma microenvironment." (PMID 35896011, 2022). "We found high GINS1/2/3/4 mRNA expression levels in sarcoma compared to non-tumor tissue." (PMID 36092720, 2022).
colon carcinoma (2 papers, 2021 to 2022). "GINS1 was required for cell proliferation in lung and colon carcinoma, and the inhibition of GINS1 suppressed the cell proliferation." (PMID 36451247, 2022). "Moreover, the IC50 values of 17 HCC and colon cancer cell lines (matched GINS1 mRNA expression and drug sensitivity data of sorafenib) were obtained from CCLE database, and showed the positive correlation between sorafenib IC50 and GINS1 expression." (PMID 34414190, 2021).
glioma (2 papers, 2021 to 2023). A benign or malignant brain and spinal cord tumor that arises from glial cells (astrocytes, oligodendrocytes, ependymal cells). "In glioma cells and tissues, GINS1 promoted cell proliferation and migration through ubiquitin-specific protease 15-mediated deubiquitination of TOP2A protein, and its high expression predicted an advanced clinical grade and a poor survival." (PMID 37627167, 2023). "Importantly, previous studies reported that AIFM3, LDHD, LYNX1, SCN2B or TMEM56 were all negatively corelated with glioma, and GINS1, KIFC1, NUF2, NUSAP1 or TPX2 were both positively related to glioma progression." (PMID 33277782, 2021).
lymphoma (2 papers, 2023 to 2025). A malignant (clonal) proliferation of B- lymphocytes or T- lymphocytes which involves the lymph nodes, bone marrow and/or extranodal sites. "Moreover, with CCK8 cell proliferation assays and colony formation assay, elevated GINS1 expression was found to be associated with doxorubicin resistance in lymphoma cells." (PMID 37576391, 2023). "Meanwhile, when GINS1 was overexpressed by lentivirus infection in these cells, GINS1 upregulation restored DOX resistance in lymphoma cells suppressed by FOXP1 silencing." (PMID 37576391, 2023). "Expression of GINS1 enhances the resistance of DLBCL cells to doxorubicin, and silencing of GINS1 weakens DOX resistance in lymphoma cells." (PMID 37576391, 2023). "In summary, this study first demonstrated that FOXP1 and its target gene GINS1 contribute to DOX resistance in lymphoma cells." (PMID 37576391, 2023). "Downregulation of FOXP1/GINS1 significantly sensitized lymphoma cells to doxorubicin." (PMID 37576391, 2023). "In an in vivo xenograft lymphoma mouse model, the FOXP1/GINS1 regulatory axis was also validated." (PMID 37576391, 2023). "While FOXP1 positively regulates the expression level of GINS1 in DLBCL and promotes DLBCL proliferation, we found that the GINS1 level was not reduced in FOXP1-deficient H1975 cells or HEK293T cells, indicating the different functions of FOXP1 in lymphoma and solid tumors." (PMID 39623140, 2025).
neutropenia (2 papers, 2021 to 2022). A decrease in the number of neutrophils found in the blood. "In the proband (II.1) described in our study, as in GINS1 deficiency, neutropenia was corrected by treatment with G-CSF." (PMID 36345943, 2022). "The mechanism by which biallelic partial LoF mutations in replicative helicase genes uniquely leads to NK cell abnormalities — and neutropenia, in the case of GINS1 deficiency — while sparing most other immune cells is poorly understood." (PMID 36345943, 2022). "In addition to the NK cell defect, the proband and his sister demonstrated neutropenia, which has been described in GINS1 deficiency, but not in MCM deficiencies." (PMID 36345943, 2022).
viral diseases (2 papers, 2023). "Isolated deficiencies of ILCs and NK cells in patients with IEIs, such as GINS1, MCM4, or MCM10 deficiency, can lead to various degrees of susceptibility to viral diseases, mostly caused by CMV." (PMID 36736301, 2023). "In some defects, such as deficiencies of MCM4, GINS1, and MCM10, where there is a significant susceptibility to recurrent and severe viral infections, the pathogenesis may be explained by severely defective NK cells." (PMID 36986362, 2023).
acute myelocytic leukemia (1 paper, 2022). "In cell cycle regulation, GINS1-knockdown caused cell cycle arrest at the quiescent G0/G1 phase in acute myelocytic leukemia and chronic myelocytic leukemia cells." (PMID 36451247, 2022).
Autoimmunity (1 paper, 2023). The occurrence of an immune reaction against the organism's own cells or tissues. "This is an AR condition caused by biallelic mutations in GINS complex subunit 1 (GINS1) gene and associated with prenatal and postnatal growth failure, dysmorphic face, dermatitis, susceptibility to infections, and autoimmunity." (PMID 36986362, 2023).
COVID-19 (1 paper, 2022). A disease caused by infection with severe acute respiratory syndrome coronavirus 2. "Moreover, the expression of GINS1 in mostly cancer tissues was higher than normal tissues, providing a rationale theoretical explanation why cancer patients infected with COVID-19 could cause the more serious condition." (PMID 36451247, 2022). "Simultaneously, we took a union of COVID-19 and all upregulated genes of 11 types of cancer to identify GINS1 as the key target." (PMID 36451247, 2022). "We revealed the GINS1 is a potential therapeutic target in cancer patients infected with COVID-19 for the first time, as COVID-19 will be a severe and prolonged pandemic." (PMID 36451247, 2022). "We identified that Go-Ichi-Ni-San complex subunit 1 (GINS1) is the potential therapeutic target in Cancer/COVID-19 by GEPIA." (PMID 36451247, 2022). "Taken together, the bioinformatics found that GINS1 mRNA and protein levels were closely connected to patients infected with COVID-19 drawing from multiple analyses, the data was only from public databases rather than own original experiments." (PMID 36451247, 2022). "Furthermore, our study provided candidate targets and compounds on GINS1 for the clinical treatment of cancer patients infected by COVID-19." (PMID 36451247, 2022). "We hypothesis GINS1 could be a potential therapeutic target for cancer patients who are infected with COVID-19." (PMID 36451247, 2022). "It indicated that GINS1 was over-expression in cancer patients who were infected with COVID-19, and might be a potential therapeutic target for them." (PMID 36451247, 2022). "Therefore, GINS1 has been considered as a promising target for the treatment of cancer patients infected with COVID-19." (PMID 36451247, 2022). "However, whether GINS1 plays a key role in cancer patients infected with COVID-19 and the effective targeting drug remains to be further investigated." (PMID 36451247, 2022). "In this study, we provided evidence that it has a high sensitivity of COVID-19 in all the 11 types of cancers (including lung, breast, colorectum, prostate, stomach, liver, esophagus, cervix, thyroid, ovary, and kidney cancer), and GINS1 played a vital role in this process." (PMID 36451247, 2022). "The expression of GINS1 may be induced in the process of COVID-19 antigen recognition." (PMID 36451247, 2022). "However, the findings have not been verified actually cancer patients infected with COVID-19, and further studies are needed to demonstrate the functions of GINS1 and the clinical treatment of the compounds." (PMID 36451247, 2022).